CTSB (cathepsin B)
Diseases named in the same sentence as CTSB in open-access papers (continued):
Sharing a sentence is not in itself a finding about the gene and the disease.
pancreatitis (continued). "In addition, cathepsin B has been involved in the progression of diseases like rheumatoid arthritis, liver fibrosis, neurological diseases, inflammatory pain, pancreatitis, hepatitis, myocarditis, cancer, and COVID-19 infection." (PMID 40427636, 2025). "Several investigations support the cathepsin B-dependent proteolytic activation of trypsinogen in experimental pancreatitis since depletion of CTSB in a knockout model or by pharmacological treatment markedly abolished trypsinogen activation and pancreatic damage." (PMID 38709385, 2024). "Similarly, we found that DRD2 activation with quinpirole downregulated the expression of CTSB in NaT-induced pancreatitis." (PMID 35927992, 2022). "Human genetic studies provided no compelling evidence for CTSB being a susceptibility gene for pancreatitis." (PMID 31235832, 2019). "According to the Cathepsin B hypothesis, mutated CTSB can lead to premature intracellular activation of trypsinogen, a key regulatory mechanism in pancreatitis." (PMID 31592339, 2019). "The cysteine protease, cathepsin B, is a potential drug target for several diseases, including, for example, various cancers, pancreatitis, liver fibrosis, rheumatoid arthritis (RA) viral Ebola, bacterial Streptococcus pneumoniae meningitis, and parasitic Trypanosoma cruzi infections." (PMID 26388830, 2015). "Cathepsin B is involved in the onset of pancreatitis and the malignant progress of tumors." (PMID 25166865, 2014). "Cathepsin B is one such candidate that could be responsible for triggering the sequence of events that leads to pancreatitis." (PMID 23409095, 2013). "· Cathepsin B has been speculated to be involved in the pathology of pancreatitis, and it could be hypothesized that similar mechanisms might, to some extent, be involved in development of T2DM." (PMID 23110768, 2012). "Since cathepsin B converts trypsinogen to trypsin while cathepsin L digests both trypsinogen and trypsin, the imbalance between cathepsin B and cathepsin L, especially insufficient cathepsin L maturation, may contribute to trypsin accumulation and development of pancreatitis." (PMID 33990205, 2021). "However, co-inheritance of the TCF7L2 variants with the pancreatitis associated susceptibility variants in SPINK1 and CTSB genes may predict the development of diabetes in these patients, but these observations need to be confirmed independently." (PMID 18706099, 2008). "Animal data as well as investigations of human samples suggest that, during pancreatitis, the lysosomal cysteine protease inhibitor CST3 undergoes redistribution into the zymogen-containing secretory compartment together with CTSB and CTSL." (PMID 39962054, 2025). "Activation of CTSB and inhibition of CTSL appear to allow for efficient trypsinogen activation and the onset of pancreatitis." (PMID 39962054, 2025). "In the zymogen fraction from Cst3−/− animals we observed significantly increased activities of CTSB and CTSL during pancreatitis, in comparison to control animals." (PMID 39962054, 2025). "Therapeutic strategies aimed at restoring the CTSB–CTSL balance or promoting CTSL maturation may help mitigate pathological trypsin activation and reduce pancreatitis severity." (PMID 41530118, 2026). "Taken together these findings suggest processing of CST3 in the zymogen granule fraction during pancreatitis which affects its inhibitory capacity for CTSB but not for CTSL." (PMID 39962054, 2025). "Here we did not observe a comparable change and the pH range of CTSB activity in zymogen granules was similar to wild-type pancreatitis mice." (PMID 39962054, 2025). "Other genetic factors related to pancreatitis are Calcium Sensing Receptor (CASR), Claudin 2 (CLDN2), Carboxyl Ester Lipase (CEL), Cathepsin B (CTSB), Myosin IXB (MYO9B), Ubiquitin Protein Ligase E3 Component N-Recognin 1 (UBR1), and Fucosyltransferase 2 (FUT2)." (PMID 36434531, 2022).
pancreatitis (continued). "Nonetheless, the T7D23A model does not rule out the possibility that CTSB-mediated trypsinogen activation can be equally effective in promoting pancreatitis with or without trypsinogen autoactivation." (PMID 31235832, 2019). "All eight nanobiosensors (arginase, cathepsin B, cathepsin E, MMP1, MMP3, MMP9, neutrophil elastase, and uPA) were used to measure enzymatic activity in serum samples from four different disease groups: localized pancreatic cancer, metastatic pancreatic cancer, pancreatitis, and a ‘healthy’ control." (PMID 40292193, 2024). "Intra-pancreatic trypsinogen activation by cathepsin B can occur in ferrets, which might trigger pancreatitis even in the absence of trypsinogen autoactivation." (PMID 30305676, 2018). "However, CTSB deletion had no impact on proinflammatory changes during cerulein-pancreatitis." (PMID 41277866, 2026). "However, the ability of cathepsin B to activate ferret trypsinogens indicates that intra-pancreatic trypsinogen activation may occur in ferrets, which can contribute to pancreatitis development even in the absence of trypsinogen autoactivation." (PMID 30305676, 2018). "In pancreatic homogenates of CTSB−/− mice treated with GPN and caerulein, no trypsinogen activation occurred, strengthening the role of CTSB as a crucial trypsinogen-activator in secretagogue-induced pancreatitis." (PMID 38709385, 2024).
Parkinson disease (23 papers, 2016 to 2025). A progressive degenerative disorder of the central nervous system characterized by loss of dopamine producing neurons in the substantia nigra and the presence of Lewy bodies in the substantia nigra and locus coeruleus. "This study focused on evaluating the degradation potential of CTSB on amyloid fibrils with varying clustering tendencies, associated with Alzheimer’s and Parkinson’s diseases, hemodialysis, and lysozyme amyloidosis." (PMID 39955315, 2025). "This study investigates the impact of cysteine protease cathepsin B (CTSB) on amyloids associated with Alzheimer’s and Parkinson’s diseases, hemodialysis, and lysozyme amyloidosis." (PMID 39955315, 2025). "Variants in the CTSB gene encoding the lysosomal hydrolase cathepsin B (catB) are associated with increased risk of Parkinson’s disease (PD)." (PMID 39587654, 2024). "This includes Parkinson’s disease-associated trans-eQTLs with 16 target genes mediated by the lysosomal protease Cathepsin B (CTSB)." (PMID 32012164, 2020). "Further functional studies will be necessary to validate not only the trans targets but also to understand mechanisms underlying Parkinson’s disease susceptibility at the CTSB locus." (PMID 32012164, 2020). "The lead trans-eSNP rs1296028 (MAF = 0.11) at the CTSB locus is associated with Parkinson’s disease susceptibility (in LD with GWAS lead SNP rs2740594; r2 = 0.68)." (PMID 32012164, 2020). "We corroborate a previously reported cis-eQTL effect on CTSB driven by a Parkinson’s disease-associated genetic variant." (PMID 32012164, 2020). "rs3947 forms an edQTL with an editing site located in the 3′ UTR of CTSB. rs3947 is in strong LD with rs2740594 (R-sq = 0.86), which is associated with Parkinson’s disease." (PMID 29527417, 2018). "Impaired cathepsin B activity has been implicated in neurodegenerative diseases such as Huntington’s, Parkinson’s and Alzheimer’s, all of which exhibit some morphological defect in lysosomes." (PMID 29883476, 2018). "Despite the growing number of evidence, the association between circulating Cathepsin B levels and Parkinson’s Disease risk is still uncertain, primarily due to the small sample sizes of the studies, limited follow-up duration, and the potential risk of reverse causality." (PMID 38790460, 2024). "Notably, CTSB-induced irreversible degradation significantly reduced the toxicity for immortalized and primary cell lines of low-clustered fibrils, such as alpha-synuclein amyloids associated with Parkinson’s disease." (PMID 39955315, 2025). "Regarding ceramide, its accumulation is crucial in the activation of CTSB in the cellular model of Parkinson’s disease." (PMID 37108361, 2023). "Furthermore, genetic variants, reduced protein levels, and diminished catalytic activity of CTSB and CTSL have been associated with neuropathology, including Parkinson’s disease, highlighting the essential role of both proteases in maintaining neuronal health." (PMID 40883786, 2025). "Together this evidence highlights CTSB as an important player in the etiology of synucleinopathies such as Parkinson’s disease, and further study of its biology may help to uncover novel therapeutic approaches to this disease." (PMID 39587654, 2024). "Replication MR analysis cathepsin B on Parkinson’s disease in FinnGen consortium." (PMID 38903897, 2024). "However, additional experimental validation is necessary to fully elucidate the role of CTSB lysosomal network in the etiology of Parkinson’s disease." (PMID 32012164, 2020). "However, recent study on α-synuclein (α-syn), that accumulates in Parkinson's disease brains, point to specific role of cysteine CtsB and L on α-syn lysosomal degradation." (PMID 27902765, 2016). "GBA1 hydrolyzes glucosylceramide into ceramide and glucose in lysosomes, and a recent study showed that CTSB is activated by ceramides to promote PSAP cleavage to saposin C, a coactivator of GBA1 in lysosomes, and that this process is altered in Parkinson disease." (PMID 38911600, 2024).
viral infection (23 papers, 2009 to 2026). "Taken together, targeting CTSB exhibits good treating effect on viral-induced AP by decreasing viral infection and pancreatic inflammatory injury." (PMID 41277866, 2026). "Mechanically, CTSB hyperactivation and inappropriate cytoplasmic translocation increase viral infections by decreasing LAMP-1 + lysosomes, exacerbating lysosomal membrane permeabilization (LMP), and enhancing exosomal release of virions." (PMID 41277866, 2026). "Hyperactivated CTSB increases viral infections by decreasing lysosomes, exacerbating LMP, and enhancing exosomal release of virions." (PMID 41277866, 2026). "Our findings highlight CTSB as a crucial modulator of lysosome function and exosome release during viral infection, providing a novel target for therapeutic intervention of CVB3-induced AP." (PMID 41277866, 2026). "The addition of EG after virus infection clearly increased the protein level of cathepsin B compared to the BVDV-infected group." (PMID 37239983, 2023). "Cathepsins of the host cell play an important role in virus infections; one of their functions is to activate virus envelope glycoproteins (e.g., CTSB)." (PMID 35629310, 2022). "Taken together, pancreatic CTSB was elevated and hyperactivated at early viral infection." (PMID 41277866, 2026). "Pharmaceutical inhibition of CTSB improves AP pathology via reducing viral infection." (PMID 41277866, 2026). "Viral infections can trigger lysosomal damage in DCs, releasing cathepsins (mainly CtsB, L, and Z) into the cytosol, where CtsB functions as an upstream NLRP3 activator; influenza virus and coxsackievirus B3 use this CtsB-dependent mechanism to enhance pyroptosis." (PMID 41369389, 2025). "Regarding the role of endo-lysosome proteases, we focused on the cysteine proteases cathepsin B and L, two highly abundant proteases in the endo-lysosome compartments, and cathepsin B and L have been previously shown to be involved in viral infections." (PMID 19619315, 2009). "In terms of cathepsin B’s mechanism of action after viral infection, our observations confirm the results of Furman’s group, and extend them by showing that not only does cathepsin B increase after viral infection, but the activity of secreted cathepsin B is also modulated." (PMID 22693552, 2012). "The observed downregulation of cathepsin B and cathepsin L-like suggests that the virus may manipulate host cell pathways by inhibiting cell death and autophagy, thereby prolonging the survival of infected cells and facilitating the persistence of viral infection." (PMID 40276510, 2025). "Based on the differential expression of virus infection-related genes (ACE2, TMPRSS2, CTSB, CTSL), a recent study claimed that endometrial tissue is likely safe from SARS-CoV-2 cell entry but susceptibility increases with age." (PMID 37142998, 2023). "In the present study, SARS-CoV-2 RNA replication was detected in fresh human cornea and conjunctiva 24 hours after viral infection, both tissues expressing SARS-CoV-2 receptor and activators ACE-2, TMPRSS2, and Cathepsin B/L with variable amount and localization." (PMID 35231027, 2022). "In addition, some host cell proteases such as cathepsin B (CTSB) and cathepsin L (CTSL) can cleave and activate the spike protein, leading to the virus infection." (PMID 35155389, 2022). "On the other hand, there was no GWAS on the association between cathepsin B/L (CTSB/CTSL) variants and viral infections, and only one GWAS identified a variant (rs4932178, T) in Furin promoter that was linked to Furin upregulation in hepatitis B patients." (PMID 33133166, 2020). "Thus, we examined the roles of these cathepsins in viral infection and found that BPIV3 entry required cathepsin B and L. Cara demonstrated that Hendra virus, an important paramyxovirus, leverages the cellular protease cathepsin L to cleave the viral F protein, which elicits fusion activity." (PMID 34072688, 2021).
colon carcinoma (22 papers, 2004 to 2025). "In snail-overexpressing HT-29 cells, CTSB activity and invadosome localization are associated with the mesenchymal phenotype in colon cancer." (PMID 37576397, 2023). "Downregulation of caveolin-1, the structural protein of caveolae, reduces the cell surface association of cathepsin B and decreases degradation of type IV collagen and invasion by the colon cancer cells, consistent with a functional role for caveolae-associated cathepsin B in invasion." (PMID 22093547, 2011). "In this study, the regulation and expression of cathepsin B (cath B) in the colon carcinoma cell line (caco-2) before and after exposure to radiation were investigated." (PMID 38003335, 2023). "This study reports that galectin-3 secretion by human colon cancer cells induces cancer cell secretion, in an autocrine/paracrine manner, of a number of proteases including cathepsin-B, MMP-1 and MMP-13." (PMID 37055381, 2023). "A previous study investigated two colon carcinoma cell lines, namely HCT-116 (with a mutated K-ras allele) and HKh-2 (with a disruption in the mutated allele), and showed that cathepsin B expression and activity are higher in HCT116 cells than in HKh-2 cells." (PMID 28402938, 2017). "Using multi-cellular tumor spheroid cocultures of colon cancer cells to reveal the mechanism, researchers have shown that cathepsin B up-regulation is mediated by the mitogen-activated protein kinase and p38 signaling pathways." (PMID 28402938, 2017). "Downregulation of caveolin-1 in the colon carcinoma cells decreases cathepsin B localization to caveolae in parallel with decreases in ECM degradation and cell invasion." (PMID 22093547, 2011). "The presence of active cathepsin B in caveolae of IBC cells suggests a potential role for this enzyme in pericellular proteolysis as was previously shown in colon carcinoma cells." (PMID 22093547, 2011). "More specifically, we have shown that in colon cancer cells cathepsin B localizes in caveolae, a membrane microdomain in which the annexin II heterotetramer is also localized." (PMID 22093547, 2011). "Similarly, a previous study indicated that suppressing Cav-1 gene expression reduces the production and secretion of cathepsin B precursors in colon cancer cells." (PMID 40135201, 2025). "Interestingly, recent studies have revealed that colon cancer cells can secrete CTSB to degrade extracellular matrix and break down cell junctions, thereby enhancing cell motility." (PMID 37923799, 2023). "We demonstrated that the novel compound was able to induce apoptosis through intrinsic and extrinsic pathways and was capable of decreasing sICAM-1, mTOR, cathepsin B concentrations, whereas increased Beclin-1 concentration was detected in both colon cancer cell lines." (PMID 33918514, 2021). "Thus, we conclude that cathepsin B activity and invadosome localization in HT-29/Snail cells is related to a mesenchymal phenotype and correlates with mesenchymal migration in colon cancer." (PMID 30818851, 2019). "Moreover, the location of cathepsin B is unchanged in most well-differentiated and half of moderately differentiated colon carcinomas, whereas this enzyme is diffusely spread throughout the cytoplasm in poorly differentiated colon carcinomas." (PMID 28402938, 2017). "The researchers speculated that active K-ras increases cathepsin B, and cathepsin B then initiates a proteolytic cascade in colon carcinoma cells." (PMID 28402938, 2017). "Compared with cathepsin B-negative tumors, cathepsin B-positive colon cancers are more likely to have K-ras and BRAF mutations and have higher multivariate hazard ratios." (PMID 28402938, 2017). "Moreover, in human colon cancer cells, caveolin-1 affects the expression and localization of cathepsin B and pro-urokinase and their receptors, thereby mediating cell-surface proteolytic events associated with invasion." (PMID 25822177, 2015).
colon carcinoma (continued). "Thus, we hypothesize that the pericellular activity of cathepsin B controls ECM proteolysis related to mesenchymal migration in colon cancer cells at early stages of the EMT." (PMID 30818851, 2019). "Furthermore, it was suggested that cystatin C and cathepsin B interaction may participate in the modulation of the invasive phenotype of human colonic tumours." (PMID 15138478, 2004). "There is an urgency to develop clinically useful agents that will be able to inhibit the action of cathepsin B. Our research demonstrated that MM131 at a dose of 3 μM significantly reduced cathepsin B concentrations in DLD-1 and HT-29 colon cancer cells." (PMID 33918514, 2021). "Here, we report that berberine induces ROS-mediated stimulation of AIF activation through cathepsin B release and PARP activation, which leads to caspase-independent cell death in colon tumor cells." (PMID 22574158, 2012). "However, in colon cancer, upregulation of CST1 neutralizes the inhibition of CTSB proteolytic activity by cystatin C and contributes to colorectal carcinogenesis." (PMID 37576397, 2023). "Thus, berberine-stimulated ROS production leads to cathepsin B release and PARP activation-dependent AIF activation, resulting in caspase-independent cell death in colon tumor cells." (PMID 22574158, 2012). "We have previously shown, using both detergent and non-detergent methods, that cathepsin B localizes to caveolae-enriched fractions of colon carcinoma and endothelial cells." (PMID 22093547, 2011).